TNF (tumor necrosis factor)
Diseases named in the same sentence as TNF in open-access papers (continued):
Sharing a sentence is not in itself a finding about the gene and the disease.
infection (continued). "Invading influenza viruses can target mouse and human lung-resident AM, which are, nevertheless, less susceptible to infection and exhibit lower virus replication and TNF production compared to monocyte-derived macrophages." (PMID 36305904, 2022). "The infection risk associated with biologic therapies targeting IL-6 or the IL-6 receptor is similar to the risk with TNF inhibitors." (PMID 35214755, 2022). "This also causes increased TNF-α release, which ultimately leads to the containment of M. tb in granulomas to prevent further spread of the infection." (PMID 35814213, 2022). "Co-culture of M2 macrophages in M2 medium also caused an increase in TNFα compared to infection in M2 medium as a monoculture." (PMID 36228018, 2022). "This infection induced the acute production of proinflammatory microglial IL-6 and TNF-α and provoked a chronic loss of microglia." (PMID 35510852, 2022). "Infection with H. pylori causes inflammation of the gastric mucosa; therefore, in the present study, TNF-α gene expression was measured in the stomach tissue as a marker of inflammation." (PMID 36139826, 2022). "TNF inhibitors increase susceptibility to infections, especially those attributed to intracellular pulmonary pathogens." (PMID 36159650, 2022). "In fact, the genes encoding proinflammatory cytokines IL-1α, IL-6, TNF-α, and IL-8 are strongly downregulated compared to infection with H. pylori alone." (PMID 36394050, 2022). "The mAb-based TNF inhibitors can be used to treat and modify the course of inflammatory conditions but cause a heightened risk of infection compared to the TNF-R-based counterpart." (PMID 36159650, 2022). "This allows for finer modulation in individuals with hyperactive immune systems to enable persistence at a level in which it can preserve some degree of the immune response to circumvent the notable infection risk imposed by TNF inhibitor usage." (PMID 36159650, 2022). "This review will then explore and evaluate how other immunomodulators and host-directed treatments influence these infections and the severity of the resulting infection to mitigate or treat TNF inhibitor-associated infections alongside antibiotics." (PMID 36159650, 2022). "The analysis restricted to the six studies including IBD patients showed that older anti-TNF users had an elevated risk of infection (OR 3.48) and malignancy (OR 3.47) than younger users." (PMID 35160280, 2022). "The improvement of TNF-α, IL-1β, IL-6, and IL-12 have been shown to be associated with the enhanced capacity of macrophages to protect against infections." (PMID 37431006, 2022). "For example, studies suggest that although increased TNFα response decreases the risk of infection, it can increase the risk of death from septic shock, should it occur." (PMID 35056044, 2022). "Due to its central role in the early innate immune response, TNF inhibition results in an increase in susceptibility to infection." (PMID 36159650, 2022). "It is known that early cytokines TNF-α and IL-6 are involved in the development of inflammation at the site of infection and cause immune activation and recruitment of macrophages." (PMID 35744668, 2022). "The infection caused the overexpression of interferon and pro-inflammatory cytokines, such as IL-1β, TNF-α, and IL-8." (PMID 35385544, 2022). "Infection with HAdV35 caused increased expression of IL-6, IL-1β, TNF-α, and especially IL-8 in both A549 and SK-OV-3 cells." (PMID 35458402, 2022). "One of the possible infection mechanisms is activation that stimulates monocytes and neutrophils to produce TNF-α, which causes tissue disruption." (PMID 35178093, 2022). "TNF-alpha shares the same characteristics and pharmacokinetics as IL-6, causing a rapid rise 2-4 hours after infection onset." (PMID 35449688, 2022). "Research showed that TNF-α-null mice were susceptible to infection, and patients with inflammatory disorders who were treated with anti-TNF agents had a high tendency for reactivation of latent TB." (PMID 36365041, 2022).
infection (continued). "As TNF-alpha is a proinflammatory cytokine, its blockage ultimately leads to both reduction of inflammation and increase of susceptibility to infection." (PMID 36359281, 2022). "H. pylori infection in children is associated with increased inflammatory cytokines release, especially those linked to the innate immune response, among them TNF-α which is increased in children more than in adults with the infection." (PMID 35799701, 2022). "When approved for treatment, the alternation of TNF-a function was associated with adverse effects ranging from infection, malignancy, autoimmune disorders, and, to a lesser extent, metabolic disturbances and weight changes." (PMID 35784983, 2022). "In peripheral tissues, IDO1 expression takes place in dendritic cells (DCs) and macrophages, as well as microglia in the CNS, and its expression is also induced by pro-inflammatory cytokines, such as IL-6, IL-1β, IFN-γ, and TNF and by underlying infections." (PMID 35281455, 2022). "In these patients, corticosteroids and anti-TNF agents have been associated with increased overall postoperative infection risk as well as intra-abdominal infection." (PMID 35947216, 2022). "Clinical use of anti-TNF therapy in chronic inflammatory diseases can increase the risk of serious infections, implicating a key role of TNF in host immune defense." (PMID 35479068, 2022). "The downside of long-term exposure to anti-TNF-α agents is its association with adverse effects, such as immune-mediated cutaneous reactions and susceptibility to infections." (PMID 35625771, 2022). "Biologic TNFα inhibitors effectively treat patients with these conditions, though treatment increases risk of certain infections." (PMID 36591258, 2022). "Compared to that of wild-type mice, the release of TNF-α was decreased in TLR2-deficient mice after infection with M. pneumoniae." (PMID 35372108, 2022). "Anti-TNF-α therapy is associated with an increased risk of infection; therefore, it is possible that vedolizumab will be used in the future as a first-line therapy in patients who are at higher risk, such as older patients." (PMID 35323234, 2022). "is associated with higher serum levels of IFABP2, and (iv) infection by protozoa promotes the increase of TNF-α in patients with RA, mostly in those under DMARDs pharmacological treatment." (PMID 35492365, 2022). "For instance, excessive accumulation of macrophages and neutrophils with an elevated expression of interleukin (IL)-1, IL-6, and tumor necrosis factor-alpha (TNF-α) is a typical feature of highly pathogenic IV infection." (PMID 34650550, 2021). "Infection of ob/ob mice with S. pneumonia, however, caused increased levels of TNF-α, macrophage inflammatory protein 2 (MIP-2), and prostaglandin E2 (PGE2) as well as a greater number of leucocytes after two days." (PMID 33810619, 2021). "Overall, data suggest that TNF inhibitor use is associated with an increased risk of infection in patients with RA." (PMID 33535498, 2021). "Infection or inflammation results in the rapid release of inflammatory associated molecules such as TNF and GM-CSF." (PMID 34576270, 2021). "Upon infection by the 4MBE variant there was a significant increase in TNF-α production by macrophages from 6 to 96 hpi and overall a sustained inflammatory response at 96 hpi." (PMID 34166469, 2021). "The finding is particularly interesting especially when we analyze the literature across different pathogenic NWHs infections that show stronger pro-inflammatory cytokine profiles characterized by IFNγ, TNFα, high levels of IL-6 as well as IL-1β." (PMID 33815363, 2021). "Risk of infections with TNF-α agents was quite similar to that due to immunosuppressive drugs (333/10,000 PYF) and was lower than that due to CS (730/10,000 PYF; IR, 0.48; 95% CI, 0.40–0.58)." (PMID 34064576, 2021). "Infection with SARS-CoV-2 virus causes the body’s immune response in which pro-inflammatory cytokines such as TNF-α, IL-6, IL-1β, IL-2 and IFN-γ are secreted." (PMID 34575258, 2021).
infection (continued). "In contrast, MAIT cells deficient in the production of TNF, IFNγ, or GM-CSF were unable to provide protection, with mice succumbing to infection similar to the untreated Rag2−/−γC−/− mice." (PMID 34272362, 2021). "Surprisingly, TNF-driven death during vMIA/vIBO-deficient mutant infection occurs independently of CASP8 and despite the presence of virus-encoded vICA." (PMID 34578288, 2021). "The disruption of this process by TNF-α inhibitors is well-documented and data suggests patients on these medications are at increased risk for infection and reactivation of granulomatous diseases." (PMID 33933122, 2021). "In mice, the amount of TNF increases after 24 h, the acute phase response, and is associated with accumulation of large numbers of leukocytes at the foci of infection." (PMID 34249777, 2021). "The TNF polymorphisms were shown to be associated with risk of infection by influenza A/H1N1 virus during the pandemic in Mexico in 2009." (PMID 33766078, 2021). "Increased GC, IFNγ, TNF and NO levels have been associated with augmented thymocyte apoptosis during infection and other conditions." (PMID 34987496, 2021). "Infection with aggregated Mtb led to an early upregulation of pro-inflammatory associated genes and enhanced TNFα signaling via the NFκB pathway." (PMID 34925266, 2021). "In contrast, anti-TNF-antibodies significantly inhibited cell death-induction by MVA-infection in Bax/Bak-double-deficient cells." (PMID 34711816, 2021). "The immunosuppressive effects and risk of secondary infection probably deter the use of anti-TNF therapeutics." (PMID 34367053, 2021). "ACOD1 serves a multifaceted role in the innate immune response to pathogen infection (bacteria and viruses) and in cytokine signaling (TNF and interferons), and is associated with both Toll-like receptor and NF-kB signaling pathways." (PMID 34399690, 2021). "A lack of type I IFN signaling was associated with the defective nature of IFN-γ, TNF-α, and NO production and susceptibility to infection." (PMID 35011636, 2021). "Differences in the infection risk between individual TNF inhibitors is difficult to determine due to the scarcity of head-to-head RCTs and the difficulties associated with cross-trial comparisons." (PMID 33535498, 2021). "It has been demonstrated that infection with O. tsutsugamushi elicits production of TNF (associated with both the acute and convalescent immune response) and increases in CD8+ T-cell populations." (PMID 34287349, 2021). "The overproduction of pro-inflammatory cytokines such as TNF-a and IL-6 plays an important role in the infection caused by S. suis." (PMID 34357984, 2021). "HF in mono-infection is associated with proinflammatory and antiviral immune markers, including TNF-α and IFN-γ." (PMID 33477581, 2021). "The present meta-analysis shows that there is an increased risk of various infections after treatment with anti-TNF agents." (PMID 34790122, 2021). "In numerous in vitro and in vivo studies, proinflammatory signals, such as TNF-α, IL-1β, and IL-6, have been implicated in deviating immune responses to infection with S. aureus and E. coli." (PMID 34222051, 2021). "Similar to B6 mice deficient in TNFα, B6D2F1 mice treated with anti-TNFα showed disease progression, with all mice succumbing to infection by day 51 (p < 0.0001)." (PMID 35174101, 2021). "The data do, however, support an association between increased TNFα relative to IL-17 in the lungs of vaccinated, infected mice and weight loss during infection." (PMID 34070048, 2021). "TNF-α is a main contributor to persistent inflammation- and infection-induced bone regeneration inhibitions; the underline mechanism is still not clear." (PMID 34853789, 2021). "For instance, systemically delivered anti-tumor necrosis factor (TNF) therapies currently come with a black box warning due to the potential for increased risk of serious infection." (PMID 34371698, 2021).
infection (continued). "The few that were reinfected fall into the category of moderate to high production of TNF-α (individuals with the TNF-α GA and AA genotypes), which appears contradictory to our observation that high levels of TNF-α are negatively associated with infection." (PMID 34007813, 2021). "The increased risk of infections is one of the most important considerations when prescribing TNF inhibitors, although the magnitude of this risk is a topic of debate." (PMID 33535498, 2021). "IBD-associated medication including steroids, immune modulators (Azathioprine) and biologics (TNF antibody) increase risk of post-operative infection complication." (PMID 34735461, 2021). "Microglia get stimulated due to aging, oxidative stress, air pollution, and infection which causes the production of pro-inflammatory mediators such as NO, TNF-α, IL-1β, iNOS, and COX2." (PMID 34122094, 2021). "Strikingly, suppression of constitutive CCL2 was observed during MVA-infection, especially in TNF-deficient cells." (PMID 34711816, 2021). "Still, all TNF-α inhibitors have a black box warning due to the risk of serious infection and malignancy." (PMID 34884596, 2021). "Infection with SARS-CoV-2 causes elevated production of pro-inflammatory cytokines such as tumor necrosis factor α (TNF-α), interleukin 6 (IL-6), and interleukin 12 (IL-12) which potentiate the innate immune response." (PMID 34690821, 2021). "During infection, the expression of IL-1β, IL-6, TNF-α, and iNOS in the Glu deficiency group was significantly decreased compared with the APEC XM infection group." (PMID 34502151, 2021). "The elevated levels of TNF-α in the spleen were associated with the induction of IL-10 expression, which significantly contributed to the establishment of infection." (PMID 34977224, 2021). "Exposure to anti-TNFα agents was associated with an increased risk of serious infections under the random-effects model (OR: 1.72, 95% CI: 1.56–1.90, p < 0.00001)." (PMID 34790122, 2021). "A meta-analysis of 71 RCTs and seven open-label extension studies in patients with RA, PsA and AS in 2014 found significant increases in the occurrence of any infections, SI and TB associated with TNF inhibitor treatment (20%, 40% and 250%, respectively)." (PMID 33535498, 2021). "Myeloid cells involving the M1 phenotype associated with TNF-α are crucial to control parasite burden in the blood during early infection, while the B cell-related responses are central for an anti-parasite defense." (PMID 34153047, 2021). "There was also a significant association of infection with the presence of TNF-α, INF-γ, and IL-22 in the urine." (PMID 34662329, 2021). "The present meta-analysis showed a statistically significant increase in overall adverse events, serious infections, and malignancies associated with the use of anti-TNFα agents." (PMID 34790122, 2021). "We have seen that OROV infects microglia and neurons, and that this infection induces inflammatory and toxic responses, with TNF-α release and loss of cell viability." (PMID 34887719, 2021). "One of the main concerns of anti-TNFα treatment is the increased risk of infection upon therapy administration, a matter extensively studied in patients with inflammatory diseases." (PMID 33540543, 2021). "In agreement with the in vivo data, both expression of OTUB1 and deletion of MLKL in OTUB1-deficient HepG2 cells reduced LDH release upon infection with Lm and stimulation with TNF." (PMID 33712742, 2021). "The present evidence suggests an increased risk of infections and malignancy after anti-TNF treatment." (PMID 34790122, 2021). "The induction of high levels of proinflammatory cytokines including TNF is a hallmark of severe and hemorrhagic CSF following infection with highly pathogenic CSFV." (PMID 34696447, 2021). "Since pericyte migration is a hallmark for BBB disruption following injury, infection and inflammation, we investigated the effects of estradiol on TNFα-induced PC migration." (PMID 34571963, 2021).
infection (continued). "Infection with M. tuberculosis (Mtb) H37Rv after the onset of dysglycemia was associated with significantly increased lung pathology, lower concentrations of TNF-α, IFN-γ, IFN-β and IL-10 and a trend towards higher bacterial burden at 3 weeks post infection." (PMID 34295838, 2021). "Although we cannot determine exact mechanisms, the reduction of TNF-α in parallel with decreasing viremia in the case of EEHV3B perhaps supports an association with fighting infection." (PMID 34793450, 2021). "TNFα-deficient mice infected with a sublethal dose, however, presented with greater lung pathology, inflammatory cell infiltration, and recovered from infection more slowly than wild type mice." (PMID 33680987, 2021). "For example, we recently showed that infection with a H1N2 variant induced a stronger cytokine response including Tumor Necrosis Factor alpha (TNFa) production than infection with the parental H1N2." (PMID 33917103, 2021). "Higher expression of TNF-α in blood preterm infants was associated with higher risk of infections and NEC." (PMID 32443898, 2020). "An interesting puzzle is the fact that an infection of a tumor necrosis factor α (TNF)-deficient host with pathogens such as bacteria or parasites that reside intracellularly inevitably ends fatally." (PMID 32760383, 2020). "TNF-α is a pro-inflammatory cytokine associated with trauma and infection but has also been associated with autoimmune processes." (PMID 32992555, 2020). "In these severe models, mediators released from mast cells, like histamine, TNF-α and IL-1β, cause septicemic shock and prevent migration of neutrophils to the site of infection, which is essential for clearing bacterial infection." (PMID 33352850, 2020). "These are key mediators in controlling infection because, for instance, tumor necrosis factor-α deficient (TNF-α)-/- and inducible nitric oxide synthase deficient (iNOS)-/- mice are highly susceptible to T. cruzi infection." (PMID 33574810, 2020). "TNF-α has previously been associated with control of trypanosome parasitemia, reducing infection associated pathology and mediating resistance during infection." (PMID 32059486, 2020). "Here, we employ fully wild-type murine cytomegalovirus (MCMV) and vICA-deficient MCMV (∆M36) to investigate the contribution of TNF signaling to apoptosis during infection of different cell types." (PMID 33126536, 2020). "Due to its different mechanism of action, vedolizumab seems to be safer than anti-TNF drugs showing lower risk of infections in both UC and CD patients." (PMID 32269571, 2020). "TNF-α is one of the most important proinflammatory cytokines, and its secretion is associated with inflammatory responses caused by infection." (PMID 32244903, 2020). "Studies vary in their findings regarding the risk of postoperative infections in patients taking TNF-alpha inhibitors whereas prior studies suggest that methotrexate is not a substantial risk factor for surgical site infection (SSI)." (PMID 32600315, 2020). "Unfortunately, due to the prominent pro-inflammatory function of TNF, administration of anti-TNF agents is associated with an increased risk of an infection, especially by intracellular pathogens and malignancies." (PMID 32760383, 2020). "(ii) Immunologic sounding: Persistent local infection caused by P. gingivalis induces the upregulation of inflammatory cascades involving IL-1, IL-6, IL-8, TNF-α, CRP, and IFN." (PMID 33202751, 2020). "Kinetics of cytokine production, including TGF-β, IL-10, IFN-γ, and TNF-α have been linked to the differential outcomes in infection with lethal and non-lethal P. yoelli, which starkly diverge within the first few days of infection." (PMID 32043415, 2020). "The high TNF-α concentration associated with non-ST5 infections at day 14 was driven by a single isolate - BMD1415." (PMID 32196550, 2020).